SNORD115-22 (small nucleolar RNA, C/D box 115-22)
Synonyms: HBII-52-22
Gene: Small nucleolar RNA gene on chromosome 15 (25,209,918 to 25,209,999, forward strand). Ensembl gene ENSG00000201326.
Gene Ontology:
Biological process: RNA processing
Cellular component: nucleolus
Homologues: Orthologues: macaque SNORD115 (99% identical). Paralogues in human: SNORD115-11 (99% identical), SNORD115-29 (99% identical), SNORD115-36 (99% identical), SNORD115-43 (99% identical), SNORD115-12 (98% identical), SNORD115-16 (98% identical), SNORD115-26 (98% identical), SNORD115-39 (98% identical), SNORD115-44 (98% identical), SNORD115-6 (98% identical), SNORD115-9 (98% identical), SNORD115-10 (96% identical), and 37 more.